IL11 (interleukin 11)
Diseases named in the same sentence as IL11 in open-access papers (continued):
Sharing a sentence is not in itself a finding about the gene and the disease.
tumor (continued). "Consistent with the proposed orthogonal tumor‐promoting activity of IL11‐dependent gp130/STAT3 signaling, tumors of bazedoxifene‐treated Apc‐mutant mice retain excessive nuclear accumulation of β‐catenin and aberrant WNT pathway activation." (PMID 30885958, 2019). "The dominance of IL-11 over IL-6 as the cytokine enabling tumor outgrowth from the gastrointestinal epithelium also extends into clinically more prevalent situations that occur independently of overt inflammation and/or colitis." (PMID 30736824, 2019). "Conversely, down-regulation of the tumor promoting cytokine Il11 with combination therapy was observed." (PMID 31921384, 2019). "IL-11, which is produced by several cell types in the tumor-stromal microenvironment, such as tumor cells, fibroblasts and osteoblasts, is a cytokine that promotes osteolysis by stimulating osteoclast formation." (PMID 29343249, 2018). "Multiple studies have shown that the IL-11/IL-11R/STAT3/NF-κB signaling axis plays important roles in tumor growth, angiogenesis, and metastasis." (PMID 30197757, 2018). "Tumor cells in bone secrete osteolytic factors, such as PTHrP and IL-11, leading to osteolytic bone resorption." (PMID 29423331, 2018). "Recently, another IL-6 cytokine family member, IL-11 was observed in high abundance in CRC tumor samples and correlated with increased phosphorylated STAT3 levels." (PMID 30572654, 2018). "Recently, non‐cell autonomous IL‐11 stimulation was shown to be sufficient to drive MDA‐MB‐468 tumor growth and metastasis in a xenograft model." (PMID 30120895, 2018). "Active TGF-β is released from bone matrix by osteoclastic resorption and further induces tumor production of osteolytic and pro-metastatic factors including PTHrP and IL-11." (PMID 29423331, 2018). "Mice with AN3CA subcutaneous xenograft tumours were treated with saline vehicle control or IL11 and tumour volume calculated." (PMID 28186993, 2017). "Nevertheless, recent data indicate the overexpression of IL-11Rα in prostate cancer, gastric cancer, lung cancer, breast cancer, colorectal cancer, and osteosarcoma, suggesting a relevant effect of IL-11 signalling in the link to inflammation and tumours." (PMID 29089667, 2017). "We found constituitve STAT3 activation, indicated by nuclear pSTAT3 immunostaining in control tumours, but increased pSTAT3 positive tumour epithelial cells in tissues from mice treated with IL11." (PMID 28186993, 2017). "A minor IL11-overexpressing subclone changed the tumour microenvironment by increasing intratumoural vascularisation and reorganising extracellular matrix, in turn increasing tumour growth." (PMID 28716075, 2017). "Subcutaneous xenograft tumours were established in female Balb/c athymic nude mice using AN3CA cells expressing IL11 and IL11Rα." (PMID 28186993, 2017). "It stimulates the tumor production of bone-active factors (PTHrP, IL-11, ET-1) and prometastatic factors (VEGF, CXCR4, CTGF, MMPs), which disrupt normal bone remodeling and promote invasion, angiogenesis, and homing of tumor cells to bone." (PMID 29156807, 2017). "IL11 administration resulted in a significant increase in tumour volume by 7 days of treatment, at which point the tumours approached our ethical maximum volume limit (977.25 mm3 ± 5.52 versus saline control 567.93 mm3 ± 10.11; p < 0.01)." (PMID 28186993, 2017). "We have determined that intratumoral connective tissue growth factor (CTGF), interleukin-11 (IL-11), and CXCR4 overexpression in primary tumor tissues is associated with BM in HCC patients." (PMID 27893432, 2016). "Our data based on protein array analyses suggest that stromal LMO2 can stimulate secretion of IL-11 which is a tumor promoting cytokine." (PMID 27028859, 2016). "To understand the effect of halofuginone on bone osteolysis, we next analyzed the expression of two osteolytic genes, RANKL and IL-11, in tumor biopsies from mice." (PMID 26015407, 2015).
tumor (continued). "Here we show that IL-1RT1-mediated signaling is dispensable for antral tumor development in the gp130757FF mouse, as well as IL-11-induced fundic atrophy and metaplasia." (PMID 25528766, 2015). "We found that expression of IL-11 gene was increased in tumour tissues compared with normal areas of tissues from the same patients." (PMID 28781374, 2015). "We propose a mechanism involving IL-11-dependent recruitment of tumor promoting MDSCs to the stomach." (PMID 25528766, 2015). "We have previously shown that Reg1 is strongly induced in antral tumours of gp130757FF mice coincident with IL-6 and IL-11 expression, and that haploinsufficiency of STAT3 results in reduced expression of Reg1, suggesting that it is a STAT3-regulated gene." (PMID 24804649, 2014). "Several in vitro and animal experiments using OSCC cells have shown that tumor cells produce several cytokines, including interleukin-6 (IL-6), IL-11, TNFα and parathyroid hormone-related protein (PTHrP)." (PMID 25373602, 2014). "Melatonin also decreases the production of PGE2 by malignant cells, which upregulates aromatase expression both in the tumor itself and in the surrounding adipose tissue and enhances the production of IL-11 by tumor cells." (PMID 25009641, 2014). "Neovasculature agent (RGD peptide), tumor stromal agent (matrix metalloproteinase), and tumor cell markers (epidermal growth factor, Her-2, interleukin 11) imaging agents were labeled with reporters." (PMID 23331017, 2013). "TNF, IFNγ, IL-6 and IL-11 gene expression were higher in non-tumor tissue from Iron/DSS and Control/DSS mice compared with colonic tissue from Iron and Control mice at day 78 (data not shown)." (PMID 24223168, 2013). "Supportive of the importance of NF-κB signaling in the pathogenesis of this tumor was our finding that 4 NF-κB target genes, IL-11, CXCL5, VEGFC, and CCL20, are on the list of strongly expressed genes from our gene expression profiling analysis." (PMID 24223206, 2013). "Our present study also shows that intra-peritoneal administration of SP can dramatically elevate the expression of pro-inflammatory cytokines IL-6 and IL-11 in HeLa cell xenograft tumours." (PMID 22442729, 2012). "In all tissues, IL11 and IL11Rα immunoreactivity was mainly localised to epithelial cells of tumour origin." (PMID 20553623, 2010). "Strong staining for both IL11 and IL11Rα was identified in tumour vascular endothelial and smooth muscle cells as recently reported." (PMID 20553623, 2010). "IL11 levels in uterine washings were very high (10-100 fold) in a cohort of women with Grade 3 cancers compared to the other tumour grades and controls." (PMID 20553623, 2010). "Intense staining for IL11 was seen in subpopulations of leukocytes infiltrating the cancer glands in four of the six Grade 3 tumours." (PMID 20553623, 2010). "IL11 increased pSTAT3/STAT3 in all tumour cell lines, while SOCS3 abundance was increased only in one tumour cell line." (PMID 20553623, 2010). "Our data demonstrated that IL11 protein was significantly elevated specifically in endometrial epithelial tumor cells early in the Grade 1 tumours compared to postmenopausal controls reflecting the data in uterine washings." (PMID 20553623, 2010). "While VEGF, PTHrP, and IL-11, all of which are critical regulators of tumor angiogenesis and osteoclast resorption, were not affected by the presence of HA, IL-8 secretion increased under these conditions." (PMID 20107512, 2010). "IL11 was detectable in 3 of 4 postmenopausal controls and in all the flushings from the Grade 1-3 tumours." (PMID 20553623, 2010). "Angiogenesis is also a key determinant of tumour formation and hence the localization of IL11 and IL11Rα to vascular smooth muscle and endothelial cells in the present study suggest a potential role in angiogenesis." (PMID 20553623, 2010).
tumor (continued). "IL11 also regulates the migration and invasion of human trophoblast, a process that is highly regulated but nevertheless has many similarities with tumour cell invasion." (PMID 20553623, 2010). "Statistical data showed that the tumor weights decreased by 94.1% after IL‐11 knockdown." (PMID 41178513, 2026). "Furthermore, tumor cell-derived factors such as parathyroid hormone-related protein (PTHrP) and interleukin-11 (IL-11) promote osteoclast activity by altering the RANKL/OPG ratio." (PMID 41230330, 2025). "Furthermore, down-regulation of YTHDF2 reduces degradation of tumor-promoting factors IL11 and SERPINE2 mRNA, thereby facilitating tumor development." (PMID 41446042, 2025). "Based on this, we hypothesise that blocking IL‐11 and IL‐6 may have synergic outcomes and improve the anti‐tumour benefit of drugs." (PMID 40673604, 2025). "Exogenous administration of IL‐11 accelerated tumour growth compared with the control group." (PMID 40673604, 2025). "-High relevance: IL-11/p-STAT3 axis critical for shaping immunosuppressive tumor microenvironment." (PMID 40650089, 2025). "A volcano plot showed significantly elevated expressions of immune markers (p adjusted < .05 with BH correction) in the tumour compartment from samples with low IL‐11 expression levels (IL‐11 Low) compared with those with high IL‐11 (IL‐11 High) expression levels." (PMID 40673604, 2025). "We generated an IL‐11 pathway‐blocking antibody, observing its anti‐tumour impact in a PDX model." (PMID 40673604, 2025). "As our DSP analysis also demonstrated, tumour samples from LUAD patients that express low levels of IL‐11 showed increased levels of immune expression markers, implying that such patients could be more susceptible to receive immunotherapy treatment." (PMID 40673604, 2025). "We propose that the therapeutic inhibition of IL‐11 might be effective in reducing tumour burden in LUAD patients expressing high levels of IL‐11." (PMID 40673604, 2025). "Notably, we also found that IL11+CD10+ iCAFs were a key component of CSC niche that drive tumor stemness in CSCs by upregulating the expression of SOX9 and OLFM4, leading to drug resistance via the AREG‐ERBB2 signaling pathway." (PMID 39950944, 2025). "Meanwhile, IL‐11 also acts on GP130 to assist tumor cells in immune escape." (PMID 39712454, 2025). "In metastatic breast cancer, elevated MAFF expression was associated with activation of the IL-11/signal transducer and activator of transcription 3 (STAT3) pathway, and inhibition of MAFF expression reduced tumor metastasis, suggesting a role in promoting tumor invasion and dissemination." (PMID 41146237, 2025). "Surprisingly, few subjects demonstrated greater IL11 mRNA in normal, compared to tumor, regions that may suggest some degree of heterogeneity in NSCLC." (PMID 39329890, 2024). "IL-11, a member of the IL-6 family of cytokines, plays a multifaceted role in different processes, such as hematopoiesis, bone formation, tissue regeneration, inflammation, and tumor progression." (PMID 39194712, 2024). "This potentially suggests that IL-11 may be used as both a diagnostic and monitoring tool for treatment responses in NSCLC, akin to CEA as a traditional tumor biomarker." (PMID 39329890, 2024). "Specifically, LIF and GM-CSF secretion was PKD-dependent in the metastatic cell lines MDA-MB-231, MDA-MB-468 and MDA-MB-436, compared to one primary tumor cell line while the secretion of IL-11 and MMP-13 was found to be regulated by PKD only in metastatic TNBC cells." (PMID 38323010, 2024).
tumor (continued). "Our results suggest that these mechanisms may be controlled in parts by the capacity of Yap to promote in tumor cells expression of IL-11, possibly through a previously identified NF-κB–dependent mechanism." (PMID 37957015, 2024). "Here, we have utilized an animal model of IGC to identify potential blood-based biomarkers unique to disease stage, in addition to biomarkers that may predict tumor regression, with a focus on therapeutic inhibition of IL-11 signaling." (PMID 38542101, 2024). "The osteolytic bone metastasis mode, most common for breast cancer bone metastases, is distinguished by osteoclastic bone destruction induced by IL-11, coupled with promotion of tumor growth and osteoblast proliferation driven by angiogenesis through the connective tissue growth factor (CTGF)." (PMID 38243240, 2024). "Since IGC in the gp130Y757F model can be reversed following therapeutic inhibition of Interleukin (IL)-11, we explored whether the protein signatures we identified could be used to monitor tumor regression." (PMID 38542101, 2024). "Moreover, IL-11 was found to promote tumor growth and metastasis, and the presence of IL-11 is now used as a biomarker for poor cancer prognosis." (PMID 38732588, 2024). "IL-11 is known to stimulate proinflammatory responses, including IL-6 and IL-33, through the JAK–STAT pathway in tissue fibroblasts, of which cancer-associated fibroblasts contribute centrally to the tumor microenvironment." (PMID 39329890, 2024). "IL-11 participates in bone resorption induced by malignant osteolysis and tumor growth." (PMID 38352248, 2023). "In turn, secreted IL11 is capable of enhancing epithelial CRC cells tumor initiation capacity." (PMID 36765091, 2023). "Thus, as the enIL‐11 cytokine binds to human IL‐11R with a tighter affinity as compared with mIL‐11R it is possible that its therapeutic efficacy in mouse tumor models will be underestimated due to less effective inhibition of endogenous mouse IL‐11 protein." (PMID 38023717, 2023). "We thus investigated whether increased intratumoral levels of IL11 may enhance tumor initiation in CRC." (PMID 36765091, 2023). "Moreover, we found that IL-11 at least partly inhibited the expression of GPR84 in the tumor microenvironment through the inactivation of STAT1." (PMID 36593458, 2023). "In mice, IL11 can inhibit the anti-tumor effect mediated by CD4+ T cells." (PMID 37274740, 2023). "Furthermore, the lncRNA-ATB facilitated the organ colonization of disseminated tumor cells through binding IL-11 mRNA, autocrine induction of IL-11, and triggering STAT3 signaling." (PMID 37426674, 2023). "LKB1 is an established tumour suppressor and IL11-mediated inactivation of LKB1, through its sequential phosphorylation at S325A (ERK) and S428A (P90RSK), leads to AMPK inactivation and mTOR activation, this sequence of events is linked with cancer cell proliferation." (PMID 38054591, 2023). "In addition, IL-11+ fibroblasts can activate tumor cells and fibroblasts by producing a large amount of IL-11 and promote tumorigenesis at the same time." (PMID 37875976, 2023). "CAFs secrete a variety of cytokines, growth factors and chemokines that form fertile soil for the growth of tumor cells; for example, CAFs secrete interleukin-6 (IL-6) or interleukin-11 (IL-11), resulting in tumor progression and the development of chemotherapeutic resistance." (PMID 36717783, 2023). "In conclusion, this study discovered a novel role of IL11 in tumor immune evasion, a finding that may provide guidance for the future exploration of IL11 targeting therapy." (PMID 37365574, 2023). "Their study showed increased levels of IL11 in grade I tumours, which could be useful as a marker for EC in future studies." (PMID 36982551, 2023). "iCAFs that are characterized with secreting abundant inflammatory factors like IL-6, IL-8 and IL-11 might participate in tumor metastasis and immune escape." (PMID 37853415, 2023).
tumor (continued). "In addition, TGF-β released from colorectal cancer cells stimulates CAFs to secrete IL-11, which feeds back to tumor cells to activate STAT3 signaling, favoring the survival of metastatic cells in the liver." (PMID 36980201, 2023). "Tumor cells in bone secrete pre-osteoclast maturing factors, such as parathyroid hormone-related protein, IL-11, and TNF-ɑ, which stimulate osteoblasts to increase RANKL and decrease osteoprotegerin (OPG) production, consequentially leading to bone destruction." (PMID 36674719, 2023). "IL-11 is a pleiotropic interleukin involved in tumor development." (PMID 36135194, 2022). "In human EC tissue, IL-11 are not merely expressed in epithelial tumor cells but also in tumor-associated vascular cells and stroma as well as the infiltrating leukocytes." (PMID 36531027, 2022). "IL-11 and IL-6 are tumor-promoting cytokines that function by various mechanisms." (PMID 35205776, 2022). "Additionally, serum IL11 concentrations were incrementally elevated with progressive disease stages which correlated with tumor size, stage, presence of metastases, and degree of differentiation." (PMID 35883698, 2022). "Moreover, iCAF was activated by tumour‐secreted IL‐1 and then increased the secretion of IL‐6, IL‐11 and LIF." (PMID 36282889, 2022). "Later studies, however, identified IL11 as a tumor-promoting cytokine instead." (PMID 35883698, 2022). "Likewise, the cells of the tumor located in the primary site produce many factors, such as IL-1, IL-6, IL-11, PDGF, MIP-1α, TNF, M-CFS, RANKL, and PTHrP, directly stimulating osteoclasts to form osteoclastic-type lesions." (PMID 36230523, 2022). "Serum IL-11 is a potential tumor biomarker for advanced prostate cancer." (PMID 36010693, 2022). "The same authors show that IL-11Rα and its ligand, IL-11, are specifically upregulated in human metastatic osteosarcoma cell lines and that the engagement of this autocrine loop leads to tumour cell proliferation, invasion, and anchorage-independent growth in vitro." (PMID 34201209, 2021). "Given that IL-11 released from IL-11+ fibroblasts activated the MEK/ERK pathway in tumor cells, IL-11 and the MEK/ERK pathway may constitute the feed-forward loop via cancer-associated IL-11+ fibroblasts and tumor cells." (PMID 33863879, 2021). "Moreover, in murine xenograft models, human tumor cell lines that ectopically express human TGFβ1 can elicit IL-11+ CAFs24." (PMID 33863879, 2021). "Since IL-11+ fibroblasts might promote tumor development, it is crucial to investigate the mechanisms by which acute inflammation or tumor cells induce IL-11 expression." (PMID 33863879, 2021). "Moreover, analysis using the human CRC database (GSE35602) revealed that the expression of some genes with high expression in IL-11+ fibroblasts was also elevated in tumor stromal compartments compared with tumor epithelial compartments." (PMID 33863879, 2021). "IL-11+ cells appear in the colon in murine tumor and acute colitis models." (PMID 33863879, 2021). "Moreover, TGFβ induces expression of a long noncoding RNA activated by TGFβ (LncRNA-ATB), which subsequently elevates IL-11 production by stabilizing Il11 mRNA in tumor cells." (PMID 33863879, 2021). "Moreover, PI3K-AKT-mTORC1 pathway, triggered by IL-11 signalling, contributes to tumour progression and metastasis." (PMID 34201209, 2021). "When tumor organoids are transplanted into the colon, IL-11+ cells appear in the tumor tissues." (PMID 33863879, 2021). "Our present results revealed that IL-11+, EpCAM+, and E-cadherin+ epithelial cells might be tumor cells themselves." (PMID 33863879, 2021). "However, the mouse group with shMAFF and IL11 overexpression showed increased tumor growth, which resulted from elevated expression of IL11." (PMID 34262028, 2021). "Indeed, Ac-KLF5 transactivates the CXCL12/CXCR4 chemokine axis, IL-11 cytokine signaling, and likely other paracrine molecules in tumor cells, as revealed by RNA-Seq, ChIP-Seq, and related analyses." (PMID 33731701, 2021).